CIAO2A (cytosolic iron-sulfur assembly component 2A)
Description:
Component of the cytosolic iron-sulfur protein assembly (CIA) complex, a multiprotein complex that mediates the incorporation of iron-sulfur cluster into extramitochondrial Fe/S proteins. As a CIA complex component and in collaboration with CIAO1 specifically matures ACO1 and stabilizes IREB2, connecting cytosolic iron-sulfur protein maturation with cellular iron regulation. May play a role in chromosome segregation through establishment of sister chromatid cohesion. May induce apoptosis in collaboration with APAF1.
Synonyms: CIA2A; FAM96A; FLJ22875
Tractability: PROTAC: ubiquitination databases record sites on it.
Gene: Protein-coding gene on chromosome 15 (64,072,114 to 64,094,262, reverse strand). Ensembl gene ENSG00000166797.
Subcellular location: Cytoplasm
Subcellular location (Human Protein Atlas): Cytosol; Nucleoplasm
Gene Ontology:
Molecular function: protein binding
Biological process: iron-sulfur cluster assembly; protein maturation
Cellular component: cytoplasm; cytosol; cytosolic [4Fe-4S] assembly targeting complex; nucleoplasm
Genetic constraint (gnomAD): Loss-of-function variants: 8 observed, 13.7 expected, observed/expected ratio (o/e) 0.58, 90% interval 0.34 to 1.05. The upper end of that interval is the gene's LOEUF score, 1.05, which puts it in group 4 of 6, group 1 being the genes least tolerant of losing a copy. Missense variants: 144 observed, 148.23 expected, observed/expected ratio (o/e) 0.97, 90% interval 0.85 to 1.12. Synonymous variants: 63 observed, 59.45 expected, observed/expected ratio (o/e) 1.06, 90% interval 0.86 to 1.31.
Homologues: Orthologues: chimpanzee CIAO2A (100% identical), macaque CIAO2A (100% identical), dog CIAO2A (96% identical), guinea pig CIAO2A (96% identical), pig CIAO2A (96% identical), mouse Ciao2a (95% identical), rabbit CIAO2A (95% identical), rat Ciao2a (94% identical), tropical clawed frog ciao2a (76% identical), Drosophila melanogaster galla-1 (52% identical), zebrafish ciao2a (34% identical). Paralogues in human: CIAO2B (43% identical).
Diseases named in the same sentence as CIAO2A in open-access papers:
CIAO2A is named in the same sentence as 10 diseases in open-access papers, as found by Europe PMC text mining. Sharing a sentence is not in itself a finding about the gene and the disease.
CIAO2A shares sentences with these, for which no sentence is quoted: tumor (3 papers); cancer (2); colitis (1); gastrointestinal stromal tumor (1); infection (1); Obesity (1); parasite infection (1); respiratory diseases (1); Sepsis (1); toxoplasmosis (1).